RNU6-256P (RNA, U6 small nuclear 256, pseudogene)
Gene: Small nuclear RNA gene on chromosome 11 (122,004,355 to 122,004,451, forward strand). Ensembl gene ENSG00000252556.
Homologues: Orthologues: chimpanzee U6 (90% identical), rabbit U6 (72% identical), mouse Gm22165 (60% identical), rat LOC120099054 (58% identical), mouse Gm26479 (53% identical). Paralogues in human: RNU6-116P (73% identical), RNU6-1175P (73% identical), RNU6-11P (73% identical), RNU6-34P (73% identical), RNU6-37P (73% identical), RNU6-398P (73% identical), RNU6-43P (73% identical), RNU6-24P (72% identical), RNU6-33P (72% identical), RNU6-42P (72% identical), RNU6-1 (71% identical), RNU6-1060P (71% identical), and 1282 more.